EFEMP1 (EGF-like fibulin extracellular matrix protein 1)
Diseases named in the same sentence as EFEMP1 in open-access papers (continued):
Sharing a sentence is not in itself a finding about the gene and the disease.
tumor (continued). "We therefore demonstrated, for the first time, that hypoxia-induced BCSC sphere formation (CD44+/CD24−/lowsubpopulation) in vitro and tumor formation in vivo were markedly suppressed by EFEMP1 knockdown." (PMID 27270657, 2016). "To further evaluate the possible function of EFEMP1 in the regulation of tumor growth in vivo, we established a xenograft model." (PMID 27351229, 2016). "In this study, we found that EFEMP1 upregulated the expression of epithelial marker and downregulated the expression of interstitial markers in EC cells and mouse disseminated tumor sections." (PMID 27015552, 2016). "In orthotopic tumor sections, we also found that E2 treatment group showed high level ERα and low expression of EFEMP1." (PMID 27015552, 2016). "Conflicting roles of EFEMP1 in cancer have been reported, including dual effects in two different tumor cell subpopulations." (PMID 27713911, 2016). "Expansion of DNA methylation in some gene promoter regions, such as EFEMP1, one of the fibulin family, with tumor progression has been reported in several malignancies." (PMID 27095449, 2016). "EFEMP1's tumor-promoting role has been related to its pro-invasive role from activation of NOTCH and/or NK-kappa B signaling." (PMID 27713911, 2016). "In particular, some of them are known to be up-regulated in tumor cells enhancing the aggressive nature of tumors (e.g. EFEMP1), promoting migration and invasion of cancer cells (e.g. GPC6) or acting as proto-oncogenes (e.g. MET)." (PMID 26918450, 2016). "EFEMP1-knockdown Hs578T cells were injected into the mammary fat pads of female nude mice, and tumor formation was monitored." (PMID 27270657, 2016). "In our previously study, we found that EFEMP1 acted as a tumor suppressor to inhibit cancer proliferation, invasion and migration." (PMID 27015552, 2016). "Extensive methylation of the EFEMP1 gene promoter can discriminate invasive from benign IPMNs with superior accuracy owing to their stepwise accumulation of tumor progression." (PMID 27095449, 2016). "Meanwhile, there was only 60% tumor formation rate in the EFEMP1-knockdown group, with small size and low growth speed." (PMID 27351229, 2016). "Collectively, EFEMP1 can be one of the regulators of AKT pathway to influence the development of tumor." (PMID 27351229, 2016). "Previous studies have shown that EFEMP1 regulates cancer in a context-dependent manner, and we have proven EFEMP1 acted as a tumor suppressor in EC." (PMID 27015552, 2016). "EFEMP1's strong tumor-suppression effect in TMC was consistent with reduction in both oxidative phosphorylation and aerobic glycolysis." (PMID 26307682, 2015). "In contrast, the tumor-promoting effect of EFEMP1 was clearly shown in the i.c. xenograft model with inoculum size of 1,000 cells." (PMID 26307682, 2015). "It has been suggested that EFEMP1 and TIMP-3 form a strong association which regulates matrix composition and affects tumor progression." (PMID 25987128, 2015). "Epigenetic silencing of the EFEMP1 promoter by DNA methylation has been identified in many tumors, extending the anti-tumor role of EFEMP1." (PMID 25987128, 2015). "Here, for the first time, EFEMP1 is shown to suppress the alteration of the tumor cell subpopulation equilibrium triggered in response to a chan­­ge of the orthotopic in vivo growth environment." (PMID 26307682, 2015). "Some researchers presumed that EFEMP1 regulated matrix composition and negatively affects tumor growth, invasion and angiogenesis by interacting with TIMP-3 and downregulating MMPs." (PMID 25987128, 2015). "To demonstrate the association between EFEMP1-mediated tumor cell invasion and MMP-2, we showed that MMP-2 protein and mRNA levels increased in 143B and U2OS cells stably transfected with EFEMP1 expression plasmid compared with the empty vector control groups." (PMID 25987128, 2015).
tumor (continued). "Because TMC and STIC of U251 differentially expressed EGFR and NOTCH1, we carried out a study on the impact of EFEMP1 on tumor heterogeneity, based on its potential twofold effect in these two different cell subpopulations." (PMID 26307682, 2015). "During the past decade, numerous reports have revealed EFEMP1 as an important player in cancer initiation and progression, by both tumor-suppressive and oncogenic effects in different cancer-cell contexts." (PMID 26307682, 2015). "According to our recent literature review, approximately 20 studies have examined the anti-tumor effects of EFEMP1." (PMID 25987128, 2015). "In the present study, we found that EFEMP1 was not only markedly induced by AEG-1 but also promoted tumor progression including migration and invasion." (PMID 25987128, 2015). "Here, we show that such conflicting roles of EFEMP1 in cancer occurrs in two cell subpopulations forming one tumor, and for the first time show EFEMP1's contradictory effect in the regulation of cellular respiration in the two cell subpopulations." (PMID 26307682, 2015). "The tumor suppressive role of EFEMP1 has been confirmed in cancers from several organs, including brain, breast, colon, lung, liver, nasopharynx, and prostate." (PMID 25594013, 2014). "EFEMP1 (Fibulin-3) is an extracellular matrix protein involved in tumor progression in several types of cancer." (PMID 24495907, 2014). "EFEMP1 can exert these tumor promoting effects through activation of the Notch signaling pathway, although EFEMP1 was also reported to activate EGFR and the downstream AKT/PI3K/mTor, and MAPK pathways." (PMID 24495907, 2014). "We have previously shown tumor suppression from stable transfection of EFEMP1 that nearly abolished U251's tumorigenicity in both s.c. and intracranial (i.c.)xenograft model systems." (PMID 25594013, 2014). "Efemp1 can conduct pro-tumorigenic as well as tumor-suppressive functions dependent on the cancer type." (PMID 23470560, 2013). "Paradoxically, EFEMP1 (fibulin-3) can also demonstrate either tumor-suppressive or oncogenic behavior tied to tissue-specific expression." (PMID 24236050, 2013). "To further explore the mechanism of EFEMP1 on tumor invasion and migration, we assayed culture supernatants from HEC-1B, RL95-2 and transfected cells for the concentration of MMP-2 and MMP-9." (PMID 23840707, 2013). "It has been previously shown that in human pancreatic adenocarcinoma, EFEMP1 expression promoted tumor growth both in vitro and in vivo." (PMID 23840707, 2013). "EFEMP1, the epidermal growth factor–containing fibulin-like extracellular matrix protein 1, functions as an oncogene or a tumor suppressor depending on the cancer types." (PMID 23840707, 2013). "Effects of EFEMP1 on tumor proliferation, invasion and migration were evaluated by MTT, plate colony formation, Transwell and wound healing assay." (PMID 23840707, 2013). "The EFEMP1 suppression of tumor onset time was nearly restored by ectopic VEGFA expression; however, overall tumor growth rate remained suppressed." (PMID 21955618, 2011). "In our GBM cell line/primary culture in vivo systems, the tumor-suppressive effect of EFEMP1 overwhelmed its pro-invasive activity." (PMID 21955618, 2011). "EFEMP1 over-expression in U251HF cells led to tumor growth suppression of s.c. tumors just as it had for i.c. tumors." (PMID 21955618, 2011). "Although over-expression of ectopic VEGFA was able to partially rescue the tumor growth from the suppression by EFEMP1, restoration of tumor growth rates were far from complete." (PMID 21955618, 2011). "The identification of proteins that are cooperative with EFEMP1 in the regulation of intracellular signaling pathways and the tumor microenvironment would distinguish the differential effect of EFEMP1 in cancer." (PMID 21955618, 2011). "In support of a possible tumor-suppression role, EFEMP1 was discovered to have an anti-angiogenic function via suppression of endothelial cell sprouting." (PMID 21955618, 2011).
tumor (continued). "The survival of mice after i.c. implantation of the EFEMP1-transfected cells was significantly prolonged (EFEMP1c6) and in some instances, animals were completely free of tumor (EFEMP1c2)." (PMID 21955618, 2011). "There was a significant suppression of tumor development from EFEMP1 via homogenous mixing with cells prior to implantation in both s.c. and i.c. xenograft systems." (PMID 21955618, 2011). "EFEMP1 protein treatment was able to antagonize the tumor promoting effect from EFEMP1 knock-down in GBM16B." (PMID 21955618, 2011). "The i.c. tumor size in mice implanted with U251HF cells plus EFEMP1 was smaller compared to cells plus vehicle." (PMID 21955618, 2011). "Most importantly we demonstrated an in vivo tumor suppression effect of EFEMP1 in both subcutaneous and intracranial xenograft models." (PMID 21955618, 2011). "Western blot and ELISA analyses of tumor lysates confirmed reduction of EFEMP1 protein levels due to shEFEMP1 expression." (PMID 21955618, 2011). "Notably, the expression levels of FCRL3 and EFEMP1 are significantly correlated with tumor differentiation, with both genes showing significantly lower expression in G2 (moderately differentiated) tumors compared to G3 (poorly differentiated) tumors." (PMID 41367615, 2025). "Additionally, a negative correlation was found between high expression of MFAP4 and EFEMP1 and tumor purity." (PMID 39822989, 2025). "However, further mechanistic studies are warranted to understand the significance of EFEMP1-dependent SCR in favouring the metastatic potential of OS cells and to dissect the interplay between tumour and stromal cells mediated by EFEMP1." (PMID 38031171, 2023). "Furthermore, we identified EFEMP1, a glycoprotein secreted by tumour cells, as a key player in the development of lung metastasis and a potential prognostic biomarker in OS patients." (PMID 38031171, 2023). "These clear pro-tumor properties highlight EFEMP1 as a putative therapeutic target." (PMID 34204134, 2021). "Notably, in univariate analysis, high EFEMP1 immunoexpression, high pT stage, metastastic lymph node, high tumor grade, vascular invasion, perineural invasion and multifocal tumors were significantly associated with worse DSS and MFS." (PMID 34204134, 2021). "Furthermore, adjusting tumor stage and grade, EFEMP1 expression status remained a significant prognostic factor for BRFS in multivariate analysis." (PMID 34204134, 2021). "Furthermore, Ingenuity Pathway Analysis showed that actin cytoskeleton signaling, tumor microenvironment pathway and mitochondrial dysfunction were significantly enriched by EFEMP1 dysregulation." (PMID 34204134, 2021). "Efemp1 and Prg4 can have either tumor-promoting or tumor-suppressive function." (PMID 32455670, 2020). "We next used Pearson's correlation analysis to examine the correlation between the serum EFEMP1 level and the EFEMP1 expression in the respective tumor samples evaluated using immunohistochemical staining and found that there was a strong correlation between the two (r = 0.49, P < 0.001)." (PMID 32280689, 2020). "In the mouse OS model, the serum EFEMP1 level was correlated with tumor progression." (PMID 32280689, 2020). "We found that the growth rate of HCC cells overexpressing EFEMP1 was slowed down in the subcutaneous tumor formation experiment in nude mice, suggesting that EFEMP1 may play a role in inhibiting cell proliferation in vitro and in vivo." (PMID 30972979, 2019). "In pancreatic adenocarcinoma, EFEMP1 expression promoted tumor growth and metastasis." (PMID 27015552, 2016). "EFEMP1's tumor-suppression property is indicated by the following." (PMID 27713911, 2016). "With respect to its tumor suppressor function in EC, EFEMP1 might be an excellent candidate for a therapeutic target in EC." (PMID 27015552, 2016). "In particular, EFEMP1 was subjected to both pro-tumor and anti-tumor activities." (PMID 27351229, 2016).
tumor (continued). "In addition, the vivo nude mice model confirmed that EFEMP1 was tightly correlated with the development of tumor." (PMID 27351229, 2016). "Moreover, remodeling of the actin cytoskeleton is required for tumor cell migration because the cytoskeleton pushes or pulls on the substrate near the cell membrane, and such changes are induced by EFEMP1 knockdown." (PMID 27270657, 2016). "We hypothesized that DNA hypermethylation in EFEMP1 promoter would expand with the tumor grade of IPMN." (PMID 27095449, 2016). "Besides, we performed immunohistochemistry to test the expression of EFEMP1, E-cadherin, Vimenten, Snail and β-catenin on tumor sections." (PMID 27015552, 2016). "EFEMP1-knockdown group revealed evident delay in tumor formation and growth." (PMID 27351229, 2016). "Our findings indicate that EFEMP1 can promote tumor development through a variety of mechanisms." (PMID 25987128, 2015). "We therefore hypothesized that the co-existence of 5% TMC in U251-NS, 5000 TMC when implanting 100,000 cells, might play a significant role in driving tumor onset by inducing angiogenesis, which was suppressed by the presence of EFEMP1." (PMID 26307682, 2015). "Together, these findings may explain the observed ability of EFEMP1 to stabilize subpopulation equilibrium in an orthotropic xenograft model in responding to changes in the tumor microenvironment." (PMID 26307682, 2015). "This seeming contradiction is apparently due to the combined effect of EFEMP1 suppression of TMC-driven tumor onset and growth, promoting STIC invasion and survival, and possibly blockage of chromosome mis-segregation of STIC in giving rise to slowly-proliferating cells with 1 copy of Chr7." (PMID 26307682, 2015). "In addition, we also tested, for the first time, the tumour site-specificity of EFEMP1 methylation, demonstrating that it is PCa-specific." (PMID 25211630, 2014). "In this setting, it is tempting to speculate whether EFEMP1 methylation levels might predict tumours more prone to progress to an androgen-independent status." (PMID 25211630, 2014). "Interestingly, the phenotypic assays showed that EFEMP1 de novo expression in PCa cell lines impacted mainly on tumour cell viability." (PMID 25211630, 2014). "The nude mouse tumor xenograft assay was used to investigate function of EFEMP1 in vivo." (PMID 23840707, 2013). "Moreover, EFEMP1 decreased secretion of MMPs and inhibited tumor cell proliferation, metastasis and invasion in vitro and suppressed tumorigenesis in nude mice." (PMID 23840707, 2013). "Based on our data, EFEMP1 is possibly a tumor suppressor in several types of cancer including MLS." (PMID 24345474, 2013). "With this observation in mind, we hypothesized that functional expression of EFEMP1 may dampen tumor metastasis in EC." (PMID 23840707, 2013). "Tumor doubling times were increased in a somewhat dose-dependent manner, being 3.14 ± 0.23 days with vehicle, 3.55 ± 0.31 days with +10 ng EFEMP1, and 4.24 ± 0.42 days in the +20 ng EFEMP1 (P = 0.046)." (PMID 21955618, 2011). "The results showed that EFEMP1 knock-down in U251HF cells did not cause significant effects on s.c. tumor growth (data not shown)." (PMID 21955618, 2011). "Our data revealed that EFEMP1 suppresses tumor growth via multiple mechanisms." (PMID 21955618, 2011). "Likewise, SMARCA2, GLCE, and EFEMP1 showed tumor-suppressor and anti-proliferative activities." (PMID 32610656, 2020). "Hence, one potential mechanism is the secretion of serum EFEMP1 from OS tumor cells." (PMID 32280689, 2020). "Collectively, EFEMP1 could promote tumor formation and growth in vivo." (PMID 27351229, 2016). "Importantly, there was a consistent and significant reduction in tumor outgrowth in mice that were injected with EFEMP1 knockdown cells compared with control cells, indicating that EFEMP1 knockdown significantly impaired the tumor initiation potential of BCSCs." (PMID 27270657, 2016).
tumor (continued). "Hence the identified ETSP from expression of EFEMP1 variant construct E5 would give stronger tumor suppression than the parental EFEMP1 in TMC by targeting EGFR and angiogenesis, and also would gain a new tumor-suppression function by targeting NOTCH." (PMID 27713911, 2016). "One of the EFEMP1 variants was identified as the sought-after ETSP, which had a stronger tumor-suppression function in TMCs by targeting EGFR and angiogenesis, and a new tumor-suppression function in STICs by targeting NOTCH signaling and MMP2-mediated cell invasion." (PMID 27713911, 2016). "The anti-tumor and pro-tumor activities of EFEMP1 may occur via different mechanisms." (PMID 25987128, 2015). "Moreover, our findings supported the tumor-promoting effects of EFEMP1." (PMID 25987128, 2015). "Although the anti-angiogenic and anti-EGFR effects of EFEMP1 may account for its anti-tumor effect in most cancer types, EFEMP1's tumor-promoting role has been related to activation of NOTCH signaling, and hence is likely associated with conditions in the stem-like cancer-cell context." (PMID 26307682, 2015). "Consistent with our study, a previous study showed that EFEMP1 was reduced in CSCC tissues, and its overexpression inhibited CSCC tumor growth." (PMID 40316017, 2025). "The ECM protein fibulin-3/EFEMP1 is a pericellular component uniquely upregulated in GBM compared with the normal brain, which promotes tumor growth and invasion." (PMID 40844085, 2025). "The high expression of MFAP4 and EFEMP1 exhibited increased stromal, immune, and ESTIMATE scores; however, they demonstrated an inverse correlation with tumor purity." (PMID 39822989, 2025). "ETS1 is a transcription factor and ETS1 gene expression correlates with AXL, IL6, and EFEMP1 in TNBC cell lines and tumor tissues." (PMID 38762181, 2024). "Conversely, ELN, EFEMP1, and UCHL1 were expressed at low levels, whereas TP63 was expressed at high levels in tumor tissues in contrast with ANT." (PMID 37441420, 2023). "Among these five genes, the SPARCL1, EFEMP1 and MFAP4 had significant highly methylation between normal and tumor tissues using GSCA online platform." (PMID 37563710, 2023). "The highly methylated level between tumor and normal tissues were ALDH1A3, EFEMP1, SPARCL1, CPXM2 and EFEMP1." (PMID 37563710, 2023). "ELN, EFEMP1, and UCHL1 were expressed at low levels whereas TP63 was expressed at high levels in tumor tissues in contrast with ANT." (PMID 37441420, 2023). "From the previous study of our group, the dysregulated proteins AMBP, KLK3, LMAN2, and TTR were found dysregulated in urine and tumor tissue from PCa patients, while SECTM1 was only found in urine from PCa patients, and CDH1 and EFEMP1 were only in PCa tissue." (PMID 35454907, 2022). "Some DEGs have been proved to play an important role in regulating tumor cell invasion ability such as WNT7A, VEGFA, EFEMP1, TRPV2, and FOXC2, whose expressions are consistent with the phenotype (see Results)." (PMID 35755807, 2022). "EFEMP1 (Fibulin‐3, FBLN3) is an EGF‐containing fibulin‐like extracellular matrix protein, which has been reported to act as both a tumour promoter and suppressor, depending on the cancer type." (PMID 34936728, 2021). "In our study, EFEMP1 expression was higher in MIBC than in NMIBC and it can predict a high bladder recurrence rate after adjusting for tumor stage and grade, suggesting the prognostic role of EFEMP1 in NMIBC." (PMID 34204134, 2021). "Hence, EFEMP1 may either promote or suppress tumor growth, depending on the context." (PMID 32280689, 2020). "To further detect the effect of EFEMP1 on the development of HCC in vivo, we performed the tumor formation experiment in nude mice." (PMID 30972979, 2019). "In this study, we examined the expression and significance of EFEMP1 in tumor tissues of HCC patients, analyzed the effects of EFEMP1 on the biological behavior of HCC cells, and initially studied the mechanism of EFEMP1 on the development of HCC." (PMID 30972979, 2019).